IL1A (interleukin 1 alpha)
Diseases named in the same sentence as IL1A in open-access papers (continued):
Sharing a sentence is not in itself a finding about the gene and the disease.
tumor (continued). "IL-1α is another cytokine which release can depend on the inflammasome activation in tumor-associated cells." (PMID 27528423, 2016). "IL1α is another cytokine which has been found to be implicated in the oxidative stress led necrotic death and consequently tumor progression." (PMID 26682000, 2016). "In sham-treated F1Bx mice, plasma levels of eotaxin at 6 hrs after treatment and IL-1A at 15 weeks after treatment were significantly associated with tumor latency." (PMID 25747469, 2015). "Our correlation study showed that variations in tumor IL-1α transcript levels were associated not only with variations of IL-1 family genes, but also with several genes related to neovascularisation." (PMID 26460957, 2015). "IL-1α is a pleotropic pro-inflammatory cytokine induced in several human cancers and has been associated with virulent tumor phenotype and poorer prognosis." (PMID 25237386, 2014). "It is also noteworthy that, unlike IL-1β, the elevated levels of IL-1α in normal skin keratinocytes was sufficiently high in this assay to mask any quantifiable effect of IL-15 on IL-1α protein expression within the underlying tumor." (PMID 24416335, 2014). "Elevated levels of tumor-cell associated IL-1α protein were present in formalin-fixed paraffin embedded sections of IL-15−/− tumors." (PMID 24416335, 2014). "Both proteins, IL-1α and -β, have been implicated in tumor progression by inducing the expression of angiogenic and metastatic genes, cytokines and growth factors, such as MMPs, VEGF, IL-6 and 8, CCl2, CCL7, TNFα and TGFβ." (PMID 24887580, 2014). "High expression of some interleukins, such as IL-1α and IL-1β, has been associated with a more aggressive tumor type and poor prognosis." (PMID 24887580, 2014). "This inhibition of tumour growth was paralleled by a >40% decrease in polymorphonuclear cell numbers, and the up-regulation of associated pro-inflammatory cytokines including IL-1α, IL-1β as well as COX2, all of which promote gastric tumourigenesis." (PMID 24804649, 2014). "Mutated Ras induces an IL-1α-dependent mechanism that leads to constitutive NF-κB activation and tumor promotion." (PMID 23847618, 2013). "Tumor cell-associated IL-1α also potentiates antigen presentation by the malignant cells themselves, possibly through IFNγ-induced MHC class II expression, and also via cross-presentation by professional APCs." (PMID 23847618, 2013). "In concert with these data, IL-1β- and IL-1α-deficient mice had decreased tumor numbers and tumor size in the MCA model of fibrosarcoma." (PMID 24273542, 2013). "It is notable that when tumor cells expressing membrane-associated IL-1α are injected into mice, anti-tumor immune responses occur without concomitant tumor-mediated suppression and thus the malignant cells are rejected." (PMID 23847618, 2013). "IL-1α-expressing tumor cells usually fail to cause tumor development in intact mice but if tumors occur, they subsequently regress." (PMID 23847618, 2013). "In its cell-associated form, IL-1α mainly acts as a tumor suppressor in malignant cells by recruiting immunocompetent cells to the tumor microenvironment and assisting in an immunologic response to combat tumor growth." (PMID 21765834, 2011). "In addition to intrinsic STAT3 activation, tumor-associated macrophages (TAMs) exacerbate muscle degeneration by secreting pro-inflammatory cytokines, particularly IL-1α and IL-6, which activate STAT3 signaling in muscle fibers." (PMID 40704145, 2025). "Furthermore, BRAF/MAPK pathway blockade is represented by inhibition of tumor-associated fibroblasts (TAFs) by modulation of interleukin-1 (IL-1), in particular by the transcription of IL-1α and IL-1β." (PMID 40872623, 2025). "TA-pDCs recovered in ascites from ovarian tumor patients secreted the proangiogenetic factors CXCL8 and TNF-α, while in non-small cell lung cancer patients, tumor-infiltrating pDCs were reported to cause tumor proliferation via the pro-angiogenic effects of IL-1α." (PMID 38504978, 2024).
tumor (continued). "Contrary to our findings showing apparent inhibition of anti-tumor immune response by IL-1α, it has also been demonstrated that the membrane-associated form of IL-1α can be efficient in activating innate anti-tumor immune responses, by acting as a focused adjuvant." (PMID 38612760, 2024). "Indeed, we found that knockout of IL-1α in 4T1 cells affected the expression of several cytokines, chemokines, and other factors associated with tumor growth and progression." (PMID 38612760, 2024). "To confirm that tumor growth inhibition in mice injected with IL-1α deficient 4T1 cells was dependent on the host immune response, we injected either 4T1/WT or 4T1 IL-1α KO cells into immunocompromised NOD.SCID mice and compared tumor growth with those from immunocompetent BALB/c mice." (PMID 38612760, 2024). "IL1A encodes IL‐1α, which, along with IL‐1β, plays a dual role in malignant tumour progression." (PMID 39602465, 2024). "Moreover, IL-1α deficiency in tumor cells reduced tumor growth even in the highly pro-inflammatory microenvironment of IL-1Ra KO mice." (PMID 38612760, 2024). "Future studies will be necessary to define the functional significance and underlying mechanisms of other tumor supportive cytokines/chemokines (i.e., IL1A/B, LIF, G/M-CSF and CXCL2/3) and inflammatory proteins (i.e., S100P and S100A9) in mediating XIST regulation of tumor growth and CSC activity." (PMID 36922677, 2023). "Altogether, CPH:SA‐based IL‐1α‐MPs demonstrated promising sustained systemic release kinetics accompanied by minimal weight loss, cytokine storm and hypotension and retention of anti‐tumor activity." (PMID 37206237, 2023). "Together, these data indicate that PyMT-B6-derived IL-1α induces a novel inflammatory phenotype in HSPCs associated with tumor-induced EMH that may be targetable therapeutically." (PMID 37134077, 2023). "Research has shown that tumor-associated macrophages (TAMs) in the tumor microenvironment are primarily composed of M2-type macrophages, which promote the expression of IL-1α, IL-1β, VEGF-A, and VEGF-C, thereby facilitating tumor growth and tumor angiogenesis/lymphangiogenesis." (PMID 38235128, 2023). "Moreover, residual tumor-promoting activity in the skin of TNF-α−/− mice was associated with induction of IL-1α and IL-1β gene expressions." (PMID 37097392, 2023). "TPM3, CHMP4C, EEF1A1, FASN, TNF, S100A10, and IL1A represent a high-risk score and poor prognosis, suggesting that these genes may be associated with the tumor process in patients with CC and appear to be pro-oncogenes." (PMID 36685937, 2022). "Another theory is that LF may inhibit tumour cells from secreting IL1-α, which causes increased tumour growth." (PMID 35204791, 2022). "Additionally, in pancreatic ductal adenocarcinoma, tumour‐associated IL‐1α release, probably through cell damage, can also induce tumour growth." (PMID 35344301, 2022). "Necrotic tumor cells release their intracellular components, some of which act as functional inflammatory mediators, the so-called damage-associated molecular patterns (DAMPs), such as IL-1α, ATP, and high mobility group box 1 (HMGB1)." (PMID 34063828, 2021). "Hence, in the context of pancreatic cancer, IL-1α expression in the presence of tumor-associated fibroblasts seemed to synergistically promote tumor growth and progression." (PMID 33430381, 2021). "The relapse-free survival period was significantly associated with the expression of tumor immune response-related genes, such as IL1A, molecular identification group (MIG), TCR repertoire clonetype, and HLA-C expression, based on both Pearson_p-value and logrank_p-value." (PMID 33476333, 2021). "In this study, the authors propose that IL-1α and β could promote tumor progression, but in association with other cytokines, in particular, those signaling a Th1 response and their effects on macrophages, they rather promote an anti-tumor immune response." (PMID 33498483, 2021).
tumor (continued). "Membrane-associated IL-1α could elevate immunogenicity of the tumour cell and exert positive effect on anti-tumour immune surveillance and tumour regression." (PMID 30819119, 2019). "The release of IL-1α appears to be associated with an anti-tumor response since increased rIL-1α can induce tumor regression as a single agent in immunocompetent mice and enhance the anti-tumor activity of cetuximab." (PMID 30890189, 2019). "Interestingly, tumor cell-associated IL-1α can also mediate the paracrine stimulation of CAFs to induce a pro-inflammatory phenotype in a co-culture model of pancreatic ductal adenocarcinoma." (PMID 31137641, 2019). "The IL-1α pathway has been implicated in a feed-forward signaling loop that leads to the production of pro-tumorigenic factors that contribute to malignant transformation, tumor formation and production of angiogenic factors, including CXCL1 and CXCL8." (PMID 29502208, 2018). "Similarly, there also exists a separate pathway in which IL-1α upregulates the release of sICAM from tumour-associated endothelial cells even in tumours expressing low levels of membrane-bound ICAM-1." (PMID 29772648, 2018). "The IL-1α gene is susceptible to epigenetic regulation; however, whether tumor-derived myeloid cells have epigenetically altered BPH-1 or TRAMP C3 cells remains to be determined." (PMID 29502208, 2018). "The expression of inflammatory-associated cytokines, including IL-1α, IL-1β and IL-6, were significantly reduced in the tumor microenvironment of JC-001-treated mice, suggesting that JC-001 might decrease tumor-induced inflammation." (PMID 28399860, 2017). "Also, IL-1α released by tumor cells stimulates the proliferation of carcinoma-associated fibroblasts and increases cytokines secretion from fibroblasts, which in turn promotes cancer progression." (PMID 26460957, 2015). "Compared with their lower metastatic counterparts, the highly metastatic tumors formed by this cell line expressed higher amounts of interleukin (IL)-1α, with similarly augmented expression of IL-1α and IL-1β by tumor stromal cells and of VEGF-A and VEGF-C by tumor-associated macrophages." (PMID 24924428, 2014). "If the level of secreted IL-1β can be suppressed (suppression of angiogenesis) and the expression of membrane associated IL-1α increased (development of anti-tumor immunity) in parallel in tumors, the anti-tumor effect of IL-1 might be augmented." (PMID 28548063, 2014). "In addition, due to the adjuvanticity of cell-associated IL-1α, tumor cell vaccines based on constitutive or transient IL-1α expression has the potential to induce anti-tumor cell immunity in patients with MRD." (PMID 23847618, 2013). "The “natural” membrane-associated form of IL-1α is important for exerting anti-tumor effects, as it acts as an adhesion-molecule, allowing efficient cell-to-cell interactions between malignant and immune effector cells that bear IL-1Rs, which enables better killing." (PMID 23847618, 2013). "To relate these findings in CAFs to tumor cell associated IL-1α, as a downstream result of p38MAPK signaling, we analyzed the IL-1α levels in the PC013 supernatants 2 days after the exposure to p38MAPK inhibitor and found significantly reduced levels of IL-1α (P = 0.038)." (PMID 23951028, 2013). "Mutated BRAF also promotes the secretion of IL-1α and IL-1β, innate inflammatory mediators which can drive tumor cells to protect themselves from immune attack by up-regulating molecules that inhibit the function of anti-tumor lymphocytes." (PMID 24829749, 2013). "We hypothesized that tumor cells creates an inflammatory microenvironment by inducing their expression of IL-1α through down-stream targets of mutated K-Ras and deciphering this could be of relevance to determine targets for treatment." (PMID 23951028, 2013). "Meanwhile, IL-1α could hinder the growth of the tumor by causing PCa’s G0–G1 cell cycle arrest." (PMID 38745115, 2024).
tumor (continued). "Interestingly, several other cytokines reported to be associated with senescence maintenance and tumor-suppression, such as IL1α, IL1β, TGF-β, and CCL5, exhibited upregulated expression in the LY2835219 monotherapy group but did not exhibit downregulated expression in the combination group." (PMID 33116117, 2020). "However, tumor development was more rapid in wild type and IL-1α deficient mice." (PMID 28927416, 2017). "Our study in a large cohort of HNSCC patients provide evidence that high levels of IL-1α expression are associated with a higher risk of distant metastasis, in terms of both local transcript in the primary tumor and ex vivo protein production by primary tumor samples." (PMID 26460957, 2015). "When cell lines from IL-1α KO mice were injected into mice, progressive tumor growth occurred, due to the pro-invasive and immunosuppressive effects of tumor cell-derived IL-1β and the absence of immunostimulatory effects of tumor cell-associated IL-1α that is missing in these cells." (PMID 23847618, 2013). "Although implicated in many biological processes, such as export of FGF1 and IL1‐α and tumour angiogenesis, the exact function of S100A13 in skeletal muscle remains elusive." (PMID 41582615, 2026). "Second, inhibiting ANGPTL4 in vivo decreased IL1A production and tumor initiation, the two probably being functionally linked as inhibiting IL1A slows down RAS‐dependent tumor initiation in a pancreatic model." (PMID 41347893, 2026). "High IL-1α expression was localized to invasive fronts, tumor budding foci, and small cell clusters—histological features often linked to EMT and local invasion." (PMID 40940885, 2025). "Interleukin-1 alpha (IL-1α) is a cytokine that can activate various aspects of anti-tumor immunity including dendritic cell (DC) activation which is critical for the recruitment of tumor infiltrating lymphocytes." (PMID 40169985, 2025). "Biomarker analysis highlights the importance of targeting the inflammatory and immune components of the TME, with tumours expressing high IL-1α and immune infiltration showing the best responses." (PMID 39820336, 2025). "Within tumour samples, high IL-1α, IL-12 and TGF-β1 immuno-expression was significantly associated with advanced UICC TNM prognostic stage and lymph node involvement." (PMID 41465261, 2025). "The elevated immuno-expression of IL-1α, IL-12, and TGF-β1 in tumour tissues was significantly associated with advanced tumour stages and nodal involvement." (PMID 41465261, 2025). "In our cohort, approximately 40% of OSCC specimens exhibited high IL-1α expression, with marked variation even within the same tumor." (PMID 40940885, 2025). "Herein, several KLF4-assocaited genes, C10orf54 and CD274 were correlated with tumor suppression, while others, including CX3CL1, TNFRSF4, and IL1A, were correlated with tumor stimulation." (PMID 40299916, 2025). "Although we found some mild CD8+ T cell dependence of IL-6, IL-10, VEGF, and IL-1α in the tumor bed of LLCova-bearing mice, the biggest difference was evident in the proinflammatory cytokines IFN-γ and TNF-α." (PMID 40553564, 2025). "This is the first study to report high IL-1α expression specifically localized to clinically relevant tumor regions, such as the invasive front and budding-like structures, in OSCC." (PMID 40940885, 2025). "We found that IL-1α was highly expressed at the invasive tumor fronts and in budding cancer cell clusters." (PMID 40940885, 2025). "2L4-8 treatment also suppressed IFN-β response pathways (downregulation of IL1a, IL1b) and tumor development-related HIF-1 signaling, while enhancing the antigen presentation-related pathway." (PMID 40695812, 2025). "Macrophage-derived TNF-α and IL-1α lead tumor cells to produce potent angiogenic factors IL-8 and VEGF, which affect angiogenesis and tumor growth." (PMID 40658605, 2025). "On the other hand, high levels of IL1A have also been found to promote tumor cell growth, invasion, and migration." (PMID 40612864, 2025).
tumor (continued). "IL-1α can have both pro-tumor and anti-tumor effects, and its role in solid tumor development is controversial." (PMID 40176808, 2025). "Meanwhile, MDSCs are found to inhibit IL‐1α signaling and consequently hinder the induction of senescence in tumor cells." (PMID 39811803, 2025). "Adenosine, uric acid, ATP, IL-1α and immunosuppression all contribute to carcinogenesis through angiogenesis, inflammation and tumor cell proliferation." (PMID 40083772, 2025). "In the tumour microenvironment, IL-1α promotes neoangiogenesis, matrix remodelling, tumour proliferation, chemoresistance, and metastases." (PMID 39820336, 2025). "Targeting this pathway with anti-IL-1α antibodies or the IL-1 receptor 1 (IL-1R1) blocker anakinra at the onset of tumor formation not only retards tumor progression but also restores myelopoiesis in older mice." (PMID 40765820, 2025). "Here, the authors use functional studies and transcriptomics to demonstrate that APOBEC3 promotes tumour progression and squamous trans-differentiation in UC through IL-1α and downstream activation of the AP-1 transcription factor." (PMID 41390483, 2025). "The anti-tumor effect of RT + IL-1α was accompanied by significantly increased infiltration of DCs in the irradiated tumor and increased CD8 + and antigen (E7)-specific CD8 + T cell infiltration in both irradiated and non-irradiated tumors." (PMID 40169985, 2025). "Suppression of IL1A expression has been shown to significantly reduce tumor growth and enhance the efficacy of nutrient-starvation therapies, such as Anlotinib." (PMID 40021759, 2025). "IL1A potentially exerts an anti-tumor effect in RCC prognosis by inducing neutrophil extracellular traps (NETs)." (PMID 40612864, 2025). "The results demonstrated that elevated expression of IL-1α, IL-12, and TGF-β1 in tumour tissues was significantly associated with advanced stage and lymph node involvement." (PMID 41465261, 2025). "IL1RAP expression has been identified on the tumor and stromal cells of multiple tumors, promoting an immunosuppressive microenvironment, and its interaction with IL1A/IL1B has also been specifically targeted in a phase 1b clinical trial." (PMID 40647416, 2025). "By quantitative PCR (qPCR), we confirmed that Il1a, Ccl2, and Ccl3 mRNAs were virtually undetected in the tumor cells but were expressed predominantly in the CD45+ hematopoietic cells and, to a lesser degree, in the VE-cadherin+GFP– endothelial cells." (PMID 40131370, 2025). "Through inflammation, immunosuppression, angiogenesis and tumor cell proliferation, ATP, IL-1α, adenosine and uric acid also contribute to carcinogenesis." (PMID 40083772, 2025). "Increased α-SMA-positive myCAFs subpopulations are normally considered to suppress tumour progression, while increased IL-1α expression can activate the generation of iCAFs and promote tumour behaviour." (PMID 40650165, 2025). "In certain contexts, SASP elements—particularly IL-1α, IL-6, and IL-8—promote the recruitment of M1-like macrophages, Th1 cells, and NK cells, facilitating the clearance of senescent tumor cells and suppressing tumor progression." (PMID 41181123, 2025). "Larger tumor size was associated with elevated levels of TNF-α (r = 0.290, P = 0.009), TNF-R2 (r = 0.318, P = 0.022), IL-1α (r = 0.309, P = 0.026), IFN-α (r = 0.349, P = 0.007), MIP-1β (r = 0.306, P = 0.031), and IL-21 (r = 0.295, P = 0.032) in VS-CM." (PMID 39923035, 2025). "A baseline sample was obtained from 17 patients, and we were able to perform IL-1α labelling on a tumour slide taken at inclusion." (PMID 39820336, 2025). "It mediates noncanonical STING activation, inducing NF‐κB signaling in HER2+ bc, while its knockout suppresses ESCC proliferation, IL‐1α secretion, and tumor progression." (PMID 41316520, 2025). "IL-1α-exposed UPP tumor organoids showed the presence of squamous differentiation characterized by an increased amount of cytoplasm and evidence of early keratin pearl formation (arrow)." (PMID 41390483, 2025).